NCKAP1 (NCK associated protein 1)
Diseases named in the same sentence as NCKAP1 in open-access papers (continued):
Sharing a sentence is not in itself a finding about the gene and the disease.
tumor (continued). "NCKAP1 is strongly associated with microsatellite instability (MSI) and tumor mutational burden (TMB)." (PMID 37928421, 2023). "Linear regression was subsequently performed between the relative mRNA levels of NCKAP1 and tumor weights, which were significantly correlated." (PMID 36639705, 2023). "In previous studies, NCKAP1 is a promoter gene of a novel cell death modality called disulfidptosis, and overexpression of NCKAP1 promotes disulfidptosis in tumor cells, thereby inhibiting tumor cells." (PMID 37426643, 2023). "The growth rate and weights in the ACHN-OE mice were distinctly lower against the control group (p < 0.05) indicating that NCKAP1 can suppress the growth of RCC tumor xenografts." (PMID 35957696, 2022). "We investigated the impact of NCKAP1 overexpression on the tumor growth properties of ACHN cells by establishing a xenograft model established in nude mice." (PMID 35957696, 2022). "After adjusting by tumor purity, we found an important biomarker of immune cell correction by NCKAP1." (PMID 35957696, 2022). "Functional assays also showed that NCKAP1 affects cancer cell proliferation, migration, and invasion, as well as inhibits tumor growth in vivo." (PMID 35957696, 2022). "Our IHC results showed that low expression of NCKAP1 correlated with tumor size, stage, and grade, confirming our previous findings." (PMID 35957696, 2022). "Nck-associated protein 1 (NCKAP1) is associated with poor prognosis and tumor progression in several cancer types, but the function and prognostic value of NCKAP1 in ccRCC remain poorly understood." (PMID 35957696, 2022). "Morever, in contrast with the NCKAP1-Vector, the NCKAP1-OE group significantly decreased expression of Ki-67 and E-cad in tumor tissues." (PMID 35957696, 2022). "To confirm the correlation between NCKAP1 expression levels in tumor cells and HCC prognoses, we compared the time to recurrence and overall survival (OS) between the two groups." (PMID 31068575, 2019). "The results showed that NCKAP1 expression levels in the cytoplasm of tumor cells varied widely among different HCC specimens." (PMID 31068575, 2019). "As a result, clinicopathological correlations and results from in vivo and in vitro models indicated that NCKAP1 was a tumor suppressor gene." (PMID 31068575, 2019). "We demonstrated that the expression NCKAP1 in tumor cells correlated with multiple clinicopathological characteristics and was an independent prognostic factor for HCC patients." (PMID 31068575, 2019). "We analyzed the relationship between NCKAP1 expression levels in the tumor cells and the clinicopathological characteristics." (PMID 31068575, 2019). "The dual role of NCKAP1 as a tumor suppressor in some contexts and potentially promoting oncogenesis in others suggests that targeted therapies modulating its activity could provide significant benefits tailored to specific cancer types." (PMID 40141455, 2025). "Finally, through external validation, we showed that NCKAP1 are correlated with tumor migration, proliferation, and invasion of LUAD cells." (PMID 38223725, 2024). "Specificly, NCKAP1 may affect prognosis by influencing tumor proliferation, invasion, and migration, while GYS1 may affect prognosis by influencing the immunosuppressive microenvironment." (PMID 38223725, 2024). "We investigated the expression of NCKAP1 using tumor tissues and blood from patient samples." (PMID 36639705, 2023). "Except for NCKAP1, other genes significantly differed between tumor and normal groups (p < 0.05)." (PMID 38035071, 2023).
tumor (continued). "A significant association was observed between low NCKAP1 expression and TNM stage, tumor size and pathological grade, whereas NCKAP1 expression displayed no apparent associations with age, gender and tumor position." (PMID 35957696, 2022). "ccRCC stages, tumor grades 1, 2, 3, and 4 also showed elevated NCKAP1 promoter methylation levels." (PMID 35957696, 2022). "Taken together, NCKAP1 and its related genes are primarily involved in tumor-related functions and playing important roles in EMT-related signaling pathways, suggesting that NCKAP1 may mediate ccRCC tumorigenesis and development." (PMID 35957696, 2022). "Similarly, a recent study discovered that NCKAP1 is highly expressed in primary non-small-cell lung cancer (NSCLC) and is significantly associated with histologic tumor grade, metastasis, and poor survival rate." (PMID 34917619, 2021). "Based on NCKAP1 expression in the tumor cell cytoplasm, patients were divided into two groups, the NCKAP1− group (negative expression in tumor cells) and the NCKAP1+ group (positive expression in tumor cells)." (PMID 31068575, 2019). "Therefore, the abnormal expression of NCKAP1 may have an effect on the processes of tumor metastasis and invasion." (PMID 38625593, 2025). "NCK-associated protein 1 (NCKAP1), an integral component of the WAVE regulatory complex, can activate the Arp2/3 complex to promote actin polymerization, and its absence hinders disulfidptosis, promotes cell survival, and potentially aids in tumor progression and treatment resistance." (PMID 40141455, 2025). "In addition, the predicted functions of NCKAP1 and tumor immune infiltrating cells were discussed." (PMID 35957696, 2022). "Thus, we focused on the aberrant expression of NCKAP1 in tumor cells." (PMID 31068575, 2019). "Specifically, an elevation in the expression levels of PRN1, OXSM, SLC3A2, and CD2AP were observed in tumor tissues, while the expression levels of DSTN, FLNA, TLN1, IQGAP1, MYL6, NCKAP1, and NDUFS1 declined in tumor tissues." (PMID 39995998, 2025). "Of course, we noticed that deletion of PIP5K1A, NCKAP1, and CYFIP1 genes also changes gene expression in certain metabolic pathways, such as cholesterol metabolism, which might also contribute to suppression of tumor cell growth induced by deficiency of these molecules." (PMID 39408874, 2024). "In this work, we found the relationship of the MMR genes and the expression of NCKAP1 and SLC7A11, which was essential to anti-tumor immunity." (PMID 38230212, 2024). "Overexpression of NCKAP1 in ACHN cells reduced proliferation, invasion and migration capacity in vitro and inhibited tumor growth in vivo." (PMID 35957696, 2022). "Taken together, these results demonstrated that NCKAP1 inhibited the growth and metastasis of ACHN tumor." (PMID 35957696, 2022). "Although there was no significance, NCKAP1 expression was increased in the tumor comparing with in the normal samples." (PMID 36639705, 2023). "We found that the expression levels of NCKAP1 were elevated in HCC tumor specimens compared with that of matched adjacent nonneoplastic tissues." (PMID 31068575, 2019). "To compare the expression pattern of NCKAP1 in HCC tumor specimens and adjacent nonneoplastic tissues, we examined the levels of NCKAP1 in three pairs of matched HCC tumor-derived and nontumor-derived specimens by qPCR." (PMID 31068575, 2019). "When compared between NCKAP1 expression, tumor grade, TNM stage, and lymph node metastasis, a negative correlation was observed, suggesting that NCKAP1 may have an antitumor effect in ccRCC." (PMID 35957696, 2022). "Moreover, NCKAP1 messenger RNA levels were also significantly higher in HCC tumor tissues compared to that of matched adjacent nonneoplastic tissues." (PMID 31068575, 2019). "Normal liver tissue had negative or medium NCKAP1, RAC1, RPN1, and WASF2 IHC staining, while tumor tissues had medium or strong staining." (PMID 38968580, 2024).
cancer (23 papers, 2019 to 2025). A tumor composed of atypical neoplastic, often pleomorphic cells that invade other tissues. "In summary, NCKAP1 has been linked to various cancers as a biomarker and has key roles in multiple cancers." (PMID 40141455, 2025). "Previous studies have shown that NCKAP1 is associated with multiple cancer types; high NCKAP1 levels are clearly associated with the clinical features of human non-small cell lung cancer (NSCLC)." (PMID 35957696, 2022). "A comprehensive analysis of NCKAP1 expression, biological function, gene mutation, immune cell infiltration, DNA methylation, and drug sensitivity profiles in pan-cancer was performed using the Timer2.0, HPA, GEPIA, STRING, cBioPortal, UALCAN and CellMiner databases." (PMID 37928421, 2023). "Past studies have revealed that NCKAP1 is associated with multiple types of human cancer." (PMID 34917619, 2021). "Therefore, NCKAP1 could be considered a cancer-associated gene with significant potential as a prognostic indicator in various types of cancers." (PMID 40141455, 2025). "We initially evaluated NCKAP1 expression levels in both malignant and healthy tissues from 34 different cancer types in the TCGA datasets." (PMID 40141455, 2025). "This comprehensive analysis highlights the diverse genetic landscape of NCKAP1 across various cancers, emphasizing its potential impact on cancer pathophysiology and its therapeutic targets." (PMID 40141455, 2025). "NCKAP1 can serve as both an immune marker and a prognostic indicator across diverse cancer types and significantly inhibits cancer cell migration and invasion as a novel prognostic marker in CRC." (PMID 40141455, 2025). "In parallel, a marked reduction in NCKAP1 protein expression was verified by UALCAN, which suggests a potential discrepancy between NCKAP1 mRNA and protein levels in various cancers, highlighting the complexity of its regulatory mechanisms." (PMID 40141455, 2025). "Nck-associated protein 1 (NCKAP1) is critical for cytoskeletal functions and various cellular activities, and deregulation of NCKAP1 in many cancers significantly influences the outcomes of malignant diseases." (PMID 40141455, 2025). "This study advances our understanding of the roles of NCKAP1 in cancer and opens new avenues for personalized treatment strategies, potentially transforming clinical practice." (PMID 40141455, 2025). "Next, we assessed the prognostic significance of NCKAP1 in diverse cancers from the TCGA dataset via the GEPIA2 tool." (PMID 40141455, 2025). "Considering the complexities revealed by our pancancer analysis, future research should focus on elucidating the mechanistic role of NCKAP1 in various cancers." (PMID 40141455, 2025). "Amplifications in genes such as SLC3A2, OXSM, and GYS1 were linked to increased expression in cancer tissues, whereas genes such as NDUFS1 and NCKAP1 showed reduced expression, underscoring the diverse impact of DRG expression on BLCA pathology." (PMID 38507521, 2024). "We also investigated the greater levels of NCKAP1 expression in 11 different cancer types, particularly DLBC and THYM." (PMID 38968580, 2024). "The disulfidptosis genes: NCKAP1, LRPPRC, SLC7A11, OXSM, SLC3A2, NDUFS1, and GYS1 occurred somatic mutations in pan-cancer, with 1 % SNV frequency." (PMID 39605832, 2024). "To investigate the role of four disulfidptosis-related genes (SLC7A11, SLC3A2, RPN1, and NCKAP1) in cancer progression, we divided TCGA patients into high and low expression groups based on the median expression levels of these four genes." (PMID 38166898, 2024). "Knocking out the NCKAP1 gene markedly suppresses the migratory ability of cancer cells, likely due to a disruption of the WASF3 complex (WASF3 requires NCKAP1 to facilitate invasion and metastasis)." (PMID 38739940, 2024).
cancer (continued). "The expression of NCKAP1 was weakly detected in normal colon epithelium and liver; nevertheless, it showed a positive correlation with the cancer stage." (PMID 36639705, 2023). "To determine the correlation between NCKAP1 and CRC metastasis, we observed that cancer cell migration and invasion were inhibited by suppressing the expression of NCKAP1 in CRC cell lines." (PMID 36639705, 2023). "As actin has an important role in cell migration and cancer metastasis, we analyzed the change in actin expression by NCKAP1." (PMID 36639705, 2023). "Previous studies showed NCKAP1 to be a cancer promoting factor in cancer patients, leading to poor prognosis." (PMID 31068575, 2019). "NCKAP1 has been known to promote the malignancy of cancer cells by disrupting the structural stability of WAS protein family member 1 (WASF1) and is correlated with poor prognosis of patients in several cancer types." (PMID 31068575, 2019). "Moreover, genome-wide CRISPR screening of SLC7A11high cancer cells identified that, in addition to the expected XC-system (SLC7A3 and SLC7A11), NCKAP1 (Nck-associated protein 1) also plays a role in promoting disulfidptosis." (PMID 40012016, 2025). "In addition, the status of NCKAP1 in various cancers, including missense, truncating, in-frame, splice, and fusion mutations, is illustrated." (PMID 40141455, 2025). "NCKAP1 is intimately involved in cellular processes such as proliferation and cancer metastasis." (PMID 38685115, 2024). "NCKAP1 levels were scored from 0 to 2, and the scores were classified by the stage of cancer." (PMID 36639705, 2023). "In conclusion, NCKAP1 is aberrantly expressed in a variety of cancer types and could be a biomarker and potential therapeutic target." (PMID 34917619, 2021). "NCKAP1 may promote the malignancy of cancer cells by disrupting the structural stability of WASF121." (PMID 31068575, 2019). "Nck-associated protein 1 (NCKAP1) as part of the WAVE (WASP-family verprolin-homologous protein) complex plays an essential role in disease pathogenesis and poor prognosis in several cancers by regulating various intracellular processes through apoptosis, migration, and invasion." (PMID 40761790, 2025). "Hence, NCKAP1 may function in an entirely different matter compared to that in other types of cancer." (PMID 31068575, 2019). "In the current study, we thoroughly examined the mRNA levels of NCKAP1, SLC7A11, WASF2, RAC1, SLC3A2, and RPN1 as well as the relationships between the mRNA levels of these six genes in pan-cancer." (PMID 38968580, 2024). "We found that the expression of GYS1 and SLC7A11 were upregulated, while those of NCKAP1, NDUFS1, NUBPL, OXSM, RPN1, and SLC3A2 were downregulated in ccRCC tissues compared with those in the para-carcinoma tissues." (PMID 38271056, 2024). "On the other hand, a new set of potential biomarkers (NCKAP1, TNFRSF12A, LAMB2, FKBP9, PFN2, TOM1L1) and expression rules for the identification of different cancers at the transcriptome level were discovered." (PMID 34917619, 2021). "Therefore, NCKAP1 may function through a different pathway in HCC than that in other cancers." (PMID 31068575, 2019). "Cancer-pathway-related KEGG enrichment analysis and KEGG pathway analyses of the top 30 upregulated and downregulated genes revealed the roles of NCKAP1 in the MAPK signaling pathway influenced by NCKAP1." (PMID 40141455, 2025). "Furthermore, NCKAP1 interacts with Heat Shock Protein 90 (HSP90), which promotes cancer cell invasion and metastasis." (PMID 38685115, 2024). "Notably, NDUFA11, OXSM, LRPPRC, NCKAP1, RPN1, SLC3A2, and SLC7A11 were upregulated in cancer tissues, while NDUFS1 showed the opposite trend." (PMID 38213838, 2023). "NCKAP1 could be a potential immune marker for various cancers (especially LUAD), providing new insights and insights for cancer therapy." (PMID 37928421, 2023).
cancer (continued). "However, the high expression of NCKAP1 in cancer cells does not solely contribute to negative outcomes; instead, it appears to exert a positive effect on treatment outcomes in some cancers." (PMID 38739940, 2024). "We found that MHC-I scores were higher in cancer cells without expression of PIP5K1A, NCKAP1, CYFIP1, DIS3, TBP, and EXCO1." (PMID 39408874, 2024).
neurodevelopmental disorder (7 papers, 2019 to 2025). A behavioral and cognitive disorder with onset during the developmental period that involves impaired or aberrant development of intellectual, motor, or social functions. "Interestingly, NCKAP1 disruptive variants lead to a neurodevelopmental disorder." (PMID 38218914, 2024).
cardiovascular diseases (1 paper, 2012). "We found that four of the predicted disease genes, namely, ATF4, MBNL1, NCKAP1 and CXCL14, have been reported to be related to cardiovascular diseases." (PMID 22923290, 2012).
infection (1 paper, 2021). The state of being infected such as from the introduction of a foreign agent such as serum, vaccine, antigenic substance or organism.
neurodegenerative disease (1 paper, 2023). A disorder of the central nervous system characterized by gradual and progressive loss of neural tissue and neurologic function. "However, only a few studies have reported an association between NCKAP1 and neurodegenerative diseases; for example, NCKAP1 gene expression is known to be reduced in AD." (PMID 37154887, 2023).
NCKAP1 also shares sentences with these, for which no sentence is quoted: non-small cell lung carcinoma (4 papers); head and neck squamous cell carcinoma (2); lung adenocarcinoma (2); arthrogryposis (1); Autoimmunity (1); cardiomyopathy (1); cholangiocarcinoma (1); colorectal cancer (1); dilated cardiomyopathy (1); Immunodeficiency (1); kidney tumor (1); lung squamous cell carcinoma (1); muscular disorders (1); pancreatic adenocarcinoma (1); periodontitis (1); prostate adenocarcinoma (1); rectal cancer (1); Salmonella Infections (1); skin cutaneous melanoma (1); speech delay (1); uterine carcinosarcoma (1); uveal melanoma (1); viruses infection (1).